IL6 (interleukin 6)
Diseases named in the same sentence as IL6 in open-access papers (continued):
Sharing a sentence is not in itself a finding about the gene and the disease.
schizophrenia (continued). "IL-2, IL-6, IL-10 are known markers of immune status in schizophrenia; and the alterations of their levels are connected with the severity of clinical symptoms and potential clinical implications." (PMID 34025476, 2021). "Taken together, both immune factors IL-6 and TNFα are increased in schizophrenia and MDD at disease onset." (PMID 33653423, 2021). "Serum IL-6 was also statistically significantly higher among patients with schizophrenia in both the crude (β =2.86, 95% CI = 1.11, 4.62, p = 0.001) and the adjusted (β =3.60, 95% CI: 1.35, 5.86, p = 0.002) models." (PMID 34465310, 2021). "This would be consistent with the fact that elevated IL-6 peripheral levels seems to be a trait marker of schizophrenia." (PMID 34501305, 2021). "We also found a positive correlation between serum QA and serum IL-6 levels in the schizophrenia and healthy control groups." (PMID 34393855, 2021). "In our previous study, we demonstrated that elevated IL-6 levels preceded the manifestation of schizophrenia-like disturbances." (PMID 33557113, 2021). "The aim of this study was to assess the level of inflammatory markers high sensitive C-reactive protein (hsCRP) and interleukin-6 (IL-6) in patients with schizophrenia." (PMID 34465310, 2021). "Meta-regression analysis showed that schizophrenia patients with a high symptom severity score before treatment had a greater change of IL-6 levels following treatment (g: −0.03; CI −0.04 to −0.01; p = 0.002)." (PMID 33653423, 2021). "First, our results indicate some evidence in support of a potential causal relationship between IL-6, IL-9, MCP-1, sIL-2Rα, and BDNF with schizophrenia, although only the association with IL-6 survived correction for multiple testing." (PMID 34280516, 2021). "In first-episode psychosis a poor response to treatment was associated with increased levels of IL-6 and IFN-γ whereas in the current sample of patients with established schizophrenia the association was related to increased levels of IL-8." (PMID 33667853, 2021). "A meta-analysis of immune parameters observed lower variability of especially IL-6 in psychosis patients, possibly indicating that immune alterations in schizophrenia patients are truly a sign of intrinsic immune dysfunction." (PMID 33653423, 2021). "Other than IL-2 and IL-6, serum levels of IL-8 have also been described as increased in patients with schizophrenia, and correlations between serum IL-2 or IL-8 concentrations at baseline and the therapeutic outcome have been reported." (PMID 33746786, 2021). "We found diagnostic increases in SERPINA3, TNFα, IL1β, IL6, and IL6ST transcripts in schizophrenia compared with controls (p < 0.02–0.001)." (PMID 31168068, 2021). "The result of the present study concurs with studies from Western countries that consistently indicate that patients with schizophrenia have high serum levels of hsCRP and IL-6." (PMID 34465310, 2021). "The levels of hsCRP and IL-6 were significantly increased among participants with schizophrenia compared to controls: hsCRP mean value 2.87 ± 5.6 vs 0.67 ± 0.6 mg/L; IL-6 mean value 6.63 ± 5.6 vs 3.37 ± 4.0 pg/ml." (PMID 34465310, 2021). "In summary, IL-6 is the most consistent increased cytokine in all phases of schizophrenia, but a large bundle of other cytokines is found to be disturbed." (PMID 32256401, 2020). "Available evidence suggests that patients with schizophrenia have higher levels of inflammatory cytokines such as IL-1, IL-6, and tumor necrosis factor-α." (PMID 33372679, 2020). "A recent study compared TSPO PET of schizophrenia patients and controls with combined peripheral and CSF measures of IL1β, IFNγ, IL-10, IL-6 and TNF-α." (PMID 32179746, 2020). "Depression and schizophrenia patients exhibit dysregulation in their immune function, and IL-1β, IL-2r, IL-6, and TNF-α have been identified as biomarkers of schizophrenia." (PMID 33613171, 2020).
schizophrenia (continued). "In the present study, we found that schizophrenia patients with olanzapine or clozapine monotherapy exhibited increased plasma levels of IL-6, IL-10, and TNF-α, which was also observed in many previous studies." (PMID 33324265, 2020). "These cytokines were selected to include those (IL-6, IL-1β, TNFα) that can be increased in the serum of patients with schizophrenia or autism spectrum disorders." (PMID 33288794, 2020). "The results of this study found that elevated IL-6 levels correlated with higher KYNA values in schizophrenia." (PMID 32061259, 2020). "Nevertheless, this report did initially find an increase of IL-6 mRNA in schizophrenia compared to controls (p = 0.04, FDR corrected), which was dismissed on the basis of further post hoc statistical procedures (principal component-based correction)." (PMID 30940904, 2020). "The exacerbated decrease in ABCG2 in the “high inflammation” schizophrenia subgroup is consistent with evidence showing that treatment with IL-1β, IL-6 and TNFα reduces both mRNA and protein expression of endothelial ABCG2 in vitro." (PMID 30214039, 2020). "We focused on two factors: the pro-inflammatory IL-6, which has a potential role in the induction of schizophrenia-like behavioural disturbances, and the anti-inflammatory IL-4, which is the main cytokine regulating the CD200–CD200R axis." (PMID 32664639, 2020). "The classification accuracy of combined cytokines, IL-4, IL-6 and IL-12, was 79% and cross-validation accuracy was 79% for schizophrenia patients with NSS compared with healthy controls." (PMID 32038109, 2020). "Exploring detailed data on immune-inflammatory disturbances in schizophrenia reveals that IL-6 is one of the most consistently disturbed cytokines in SZ." (PMID 32256401, 2020). "We find ~38% of schizophrenia cases have a significant increase in mRNA levels of interleukin (IL)-1β, IL-6, IL-8 and SERPINA3 in both the dorsolateral prefrontal cortex (DLPFC) and the orbitofrontal cortex (OFC)." (PMID 30214039, 2020). "The effective classification accuracy of the combination (IL-4, IL-6 and IL-12) was 77% and the cross-validation accuracy was 76% in schizophrenia patients." (PMID 32038109, 2020). "For example, it was reported that there was a cytokine imbalance in people with schizophrenia, as in vivo IL-1RA, soluble IL-2 receptor, and IL-6 were found to be increased." (PMID 33013335, 2020). "The AUCs for the combined cytokines (IL-4, IL-6 and IL-12) was 0.75 (95% CI = 0.69 - 0.80) between schizophrenia patients and healthy controls." (PMID 32038109, 2020). "This research is part of a growing body of literature that treats schizophrenia as an autoimmune disease, whereby interleukin-6 is activated by the kynurenic acid pathway and significantly contributes to the symptoms of schizophrenia." (PMID 33023061, 2020). "With regard to schizophrenia, the Th17 signaling pathway, IL-6, and TNF-α are also associated with the development and aggravation of schizophrenia." (PMID 32987907, 2020). "There is a positive association between the proinflammatory cytokine IL-6 and both the KYN/TRP and KYNA/TRP ratios in CSF of patients with schizophrenia, and this finding highlights the interaction between activation of inflammation and the KYN/TRP ratio." (PMID 30940904, 2020). "Activated inflammatory microglia release pro-inflammatory cytokines such as TNF-α, IL-1β, and IL-6 and the specific influence of these inflammatory cytokines on neurotransmitter systems reportedly leads to schizophrenia and other psychiatric disorders." (PMID 32341334, 2020). "Smith and his colleagues found that the adult offspring of mice prenatally administered IL-6 displayed schizophrenia-like deficits, and that the coadministration of an anti-IL-6 antibody to the mouse model prevented the aberrant phenotype." (PMID 30836963, 2019). "Secondly, we used the following keyword search terms: ‘schizophrenia’ and ‘cognitive’ or ‘cognition’ and ‘IL-6′." (PMID 30678202, 2019).
schizophrenia (continued). "The important role that IL-6 plays in the development and symptomatology of schizophrenia, as well as how exercise can modulate the IL-6 response, is also starting to be understood." (PMID 30678202, 2019). "In schizophrenia, many reports have described raised levels of cytokines, for example, IL-6; and meta-analyses have confirmed these findings." (PMID 31214060, 2019). "In two studies that measured the levels of cytokines before schizophrenia presentation, individuals who developed the disease in the following years had higher baseline levels of IL-6 compared to others." (PMID 31908647, 2019). "There is a lot of evidence in the literature regarding immune system deregulation and the presence of high levels of pro-inflammatory cytokines such as IL-6 in patients with schizophrenia." (PMID 30678202, 2019). "First of all we used the following keyword search terms: ‘schizophrenia’ and ‘exercise’ or ‘physical activity’ and ‘IL-6′." (PMID 30678202, 2019). "In this review we examine the current evidence for the roles that exercise and the immune system play in patients with schizophrenia, and specifically analyze the interleukin-6 (IL-6) pathway as a potential mechanism resulting in these positive effects." (PMID 30678202, 2019). "In our cohort, participants with schizophrenia had higher IL-6 mRNA levels at baseline, with BIX treatment significantly increasing these levels." (PMID 31185023, 2019). "For example, the polymorphisms of interleukin (IL) -10, IL-6 and tumor necrosis factor α (TNF-α) are related to a high risk of developing schizophrenia and their levels in blood are higher in schizophrenia patients compared with healthy subjects." (PMID 30792621, 2019). "IL-6 is an immunity factor consistently demonstrated to be elevated in participants with schizophrenia." (PMID 31185023, 2019). "Elevated expressions of IL-6, IL-1β, IL-8, and SERPINA (a serine protease inhibitor) were associated with a higher WM neuron density below the orbitofrontal cortex in schizophrenia." (PMID 30792621, 2019). "Cultured cells, mouse cortex, or striatum was harvested, RNA extracted and RT-PCR conducted for several schizophrenia candidate genes: IL-6, Gad1, Nanog, KLF4, Reln, and Bdnf9a." (PMID 31185023, 2019). "Moreover, high levels of IL-6 are associated with the altered brain morphology and the severity of the disease as well as with the continuing cognitive deterioration and decline in visual attention, processing speed, working memory, and executive-control function seen as schizophrenia progresses." (PMID 30678202, 2019). "It is also worth noting that many of the cytokines altered in the maternal serum are also elevated in the blood of patients with schizophrenia, including IL-1β, IL-2, IL-6, IL-12 and TNF-α." (PMID 30691477, 2019). "The keyword search terms used were as follows: ‘schizophrenia’ and ‘exercise’ or ‘physical activity’ and ‘cognitive’ or ‘cognition’ and ‘IL-6′." (PMID 30678202, 2019). "In chronic states, IL-6 was elevated in all three disorders, while IL-1β and sIL-2R were elevated in schizophrenia and bipolar disorder." (PMID 30766494, 2018). "A recent meta-analysis that included 32 studies also found that IL-6 and IL-8 were significantly elevated in schizophrenia." (PMID 30766494, 2018). "A recent meta-analysis of 18 schizophrenia, 16 bipolar disorder, and 12 major depressive disorder studies revealed significant elevations of IL-6, TNF-α, IL-1 receptor antagonist, and soluble IL-2 receptor in acute episodes of all groups compared to controls." (PMID 29803226, 2018). "In comparison to controls, schizophrenia patients had higher levels of IL-2 (U = 1573.5, p < 0.001) and also the inflammatory cytokines IL-1β (U = 1565.5, p = 0.011), IL-6 (U = 1975.5, p = 0.018), and IFN-γ (U = 2076.0, p = 0.018)." (PMID 29803226, 2018).
schizophrenia (continued). "A meta-analysis including 16 studies comparing schizophrenia with healthy controls, found increased CSF levels of IL-1β, IL-6, IL-8, kynurenine, and kynurenic acid, while sIL-2R was decreased." (PMID 30766494, 2018). "A quantitative review of 62 studies that included 2298 individuals with schizophrenia and 1858 controls found that plasma/sera levels were increased for interleukin (IL)-1 receptor antagonist, soluble IL-2 receptor, and IL-6 in individuals with schizophrenia." (PMID 29803226, 2018). "Among the pro-inflammatory cytokines, IL-6 is found most often to be elevated in patients with schizophrenia, and has also been suggested as a possible state marker for acute relapse." (PMID 30766494, 2018). "Elevated levels of cortisol, the end hormone produced by the activation of the hypothalamic–pituitary–adrenal (HPA) axis, and of inflammatory markers, such interleukin (IL)-6, have been consistently shown in first-episode, drug-naive schizophrenia patients." (PMID 29020988, 2017). "IL-1β and IL-6 levels have been reported to be elevated in the cerebrospinal fluid (CSF) of schizophrenia patients." (PMID 28418288, 2017). "Induced viral or bacterial infection with IL-6 in pregnant mice produces intermediate phenotypes that are related to adult offspring schizophrenia." (PMID 29163240, 2017). "Recently population-based longitudinal studies have shown that elevated IL-6 and CRP levels in childhood or adolescence are associated with increased risk of developing psychotic symptoms and schizophrenia subsequently in adulthood." (PMID 28418288, 2017). "When the MIA model was performed in the inducible DISC1 knockdown mice, it led to more exacerbated schizophrenia phenotypes, compared with either single operation, and also a more exacerbated increase in IL-6 in fetal brain." (PMID 28870209, 2017). "Using quantitative RT-PCR, we measured five cytokine mRNAs (IL-1β, IL-2 IL-6, IL-8 and IL-18) from peripheral blood of healthy controls and of people with schizophrenia or schizoaffective disorder (n = 165)." (PMID 28923068, 2017). "Elevated levels of IL-6 have been measured in the cerebrospinal fluid of schizophrenia patients by others." (PMID 29163240, 2017). "We found an overall decrease in the anti-inflammatory IL-2 mRNA (p = 0.006) and an increase in three serum cytokines, IL-6 (p = 0.010), IL-8 (p = 0.024) and TNFα (p < 0.001) in people with schizophrenia compared to healthy controls." (PMID 28923068, 2017). "Renewing interest in immune aspects of schizophrenia and new findings about the brain-fat axis encourage us to discuss the possible role of interleukin-6 (IL-6) in schizophrenia." (PMID 29163240, 2017). "In the post-mortem orbitofrontal brain studies in people with schizophrenia, IL-6 mRNA significantly positively correlated with antipsychotic lifetime and daily mean intake." (PMID 29163240, 2017). "It has been shown that patients with schizophrenia have higher plasma levels of IL-6 and significant correlation of cytokine plasma levels with body mass index was established." (PMID 29163240, 2017). "Recently, it has been shown that individuals with schizophrenia have higher plasma levels of IL-6 that are correlated with depressive symptoms and worse mental and physical well-being." (PMID 29163240, 2017). "It seems that IL-6 can have a phase specific role in schizophrenia evolution, in the context of acute inflammation, chronic inflammation, and/or autoimmunity." (PMID 29163240, 2017). "More recently, an association was described between elevated serum IL-6 and VEGF levels in schizophrenia, supporting the role of inflammation in inducing BBB hyperpermeability in schizophrenia." (PMID 28588507, 2017). "In our analysis of protein levels of cytokines, we found significant increases in serum protein levels for the cytokines IL-6, IL-8 and TNFα in the whole group of people with schizophrenia compared to the whole group of healthy controls." (PMID 28923068, 2017).
schizophrenia (continued). "Treatment-resistant schizophrenia is associated with increased IL-6 sera level, and the relationship between higher IL-6 level and cognitive decline in schizophrenia has been observed, thus implicating the impact of IL-6 on behavioral aspects of schizophrenia." (PMID 29163240, 2017). "We try to enlighten some metabolic aspects of IL-6 in schizophrenia and introduce some new drug-targets." (PMID 29163240, 2017). "Further, decrease of IL-6 in the plasma of patients with exacerbation of schizophrenia was shown after discontinuation of the haloperidol therapy." (PMID 29163240, 2017). "As our patient population showed an increase in both CSF and plasma concentrations of IL-6, a cytokine released by microglia during inflammation, we cannot discount a key role of glial cell activation and immune response in recent-onset schizophrenia." (PMID 27070405, 2016). "Our work merges these two concepts to examine the predictive value of PBMC IL-6 mRNA levels in schizophrenia." (PMID 27206977, 2016). "Among cytokine genes, significant association was observed with pro-inflammatory cytokine gene polymorphisms of IL1A, IL6, TNFA, and IFNG with schizophrenia in our study population." (PMID 27177030, 2016). "First and foremost, IL-6 and sIL-6R serum levels are significantly elevated in patients with schizophrenia, with implications for symptom severity." (PMID 27206977, 2016). "This suggests that even when statistically controlling for the medication dose, IL-6 expression accounts for 19.4% of the variance in grey matter volume in people with schizophrenia." (PMID 27959331, 2016). "Last, we investigated the mRNA expression levels of MAPK14, GFAP and the inflammation markers, IL1B and IL6 in postmortem brain tissues from schizophrenia patients." (PMID 27801899, 2016). "Activation of cytokines is directly relevant to schizophrenia as studies in human subjects found elevated levels of IL-6 in the cerebrospinal fluid of Sch patients in comparison to their age and sex-matched healthy counterparts." (PMID 27746712, 2016). "Observations on genetic association in the present study also indicate that pro-inflammatory cytokines are more likely to be amplified through molecular heterotic effect of IL6 and TNFA towards the risk of developing schizophrenia in South Indian population." (PMID 27177030, 2016). "Increased serum concentrations of IL-2, IL-6, and IL-8 have been observed in patients with schizophrenia." (PMID 27047333, 2016). "The present study provides evidence of strong independent associations of pro-inflammatory cytokine genes IL1A, IL6, TNFA, and IFNG with schizophrenia and their interactions in Dravidian South Indian population." (PMID 27177030, 2016). "The plasma IL-6 and IFNγ levels were significantly higher in patients with recent onset of schizophrenia compared with controls after excluding these values (P=0.001 and 0.009, respectively)." (PMID 27070405, 2016). "In schizophrenia, serum IL-6 levels are positively correlated with PANSS Scores, an association our data replicates and extends on by examining this correlation with PBMCs." (PMID 27206977, 2016). "We discovered that participants with a diagnosis of schizophrenia had significantly higher IL-6 mRNA levels when compared to normal controls (U = 632.5, p < 0.001)." (PMID 27206977, 2016). "A two-sample Kolmogorov-Smirnov (KS) test was used to compare the distributions of IL-6 mRNA levels between controls and participants with schizophrenia." (PMID 27206977, 2016). "Nevertheless, the patients with recent onset of schizophrenia showed a significant increase in IL-6 in both plasma (P<0.001) and CSF (P=0.02)." (PMID 27070405, 2016). "For example, a cutoff of 6.0 in our sample would be five times more likely to make a correct diagnosis of schizophrenia based solely on IL-6 mRNA levels in PBMC." (PMID 27206977, 2016).